SRPRA (SRP receptor subunit alpha)
Description:
Component of the signal recognition particle (SRP) complex receptor (SR). Ensures, in conjunction with the SRP complex, the correct targeting of the nascent secretory proteins to the endoplasmic reticulum membrane system. Forms a guanosine 5'-triphosphate (GTP)-dependent complex with the SRP subunit SRP54. SRP receptor compaction and GTPase rearrangement drive SRP-mediated cotranslational protein translocation into the ER.
Synonyms: SR-alpha; SRPR; SRP-alpha; Sralpha; DP
Tractability: Small molecule: a structure with a bound ligand is known. Antibody: UniProt places it where antibodies can reach, with medium confidence. PROTAC: ubiquitination databases record sites on it; its protein half-life has been measured; a small molecule that binds it is known.
Gene: Protein-coding gene on chromosome 11 (126,262,912 to 126,269,144, reverse strand). Ensembl gene ENSG00000182934.
Subcellular location: Endoplasmic reticulum membrane
Pathways (Reactome):
Cellular responses to stimuli: XBP1(S) activates chaperone genes
Metabolism of proteins: SRP-dependent cotranslational protein targeting to membrane
Gene Ontology:
Molecular function: protein binding; RNA binding; GTPase activity; signal recognition particle binding; GTP binding
Biological process: cotranslational protein targeting to membrane; protein targeting to ER; SRP-dependent cotranslational protein targeting to membrane, signal sequence recognition; intracellular protein transport; SRP-dependent cotranslational protein targeting to membrane
Cellular component: extracellular exosome; membrane; signal recognition particle receptor complex; endoplasmic reticulum membrane
Genetic constraint (gnomAD): Loss-of-function variants: 30 observed, 64.19 expected, observed/expected ratio (o/e) 0.47, 90% interval 0.35 to 0.63. The upper end of that interval is the gene's LOEUF score, 0.63, which puts it in group 2 of 6, group 1 being the genes least tolerant of losing a copy. Missense variants: 759 observed, 872.22 expected, observed/expected ratio (o/e) 0.87, 90% interval 0.82 to 0.92. Synonymous variants: 324 observed, 318.43 expected, observed/expected ratio (o/e) 1.02, 90% interval 0.93 to 1.12.
Homologues: Orthologues: chimpanzee SRPRA (100% identical), macaque SRPRA (99% identical), rabbit SRPRA (99% identical), rat Srpra (97% identical), guinea pig SRPRA (97% identical), pig SRPRA (97% identical), mouse Srpra (97% identical), dog SRPRA (78% identical), tropical clawed frog srpra (73% identical), zebrafish srpra (68% identical), Drosophila melanogaster SrpRalpha (52% identical), Caenorhabditis elegans F38A1.8 (48% identical). Paralogues in human: SRP54 (12% identical).
Diseases named in the same sentence as SRPRA in open-access papers:
SRPRA is named in the same sentence as 4 diseases in open-access papers, as found by Europe PMC text mining. Sharing a sentence is not in itself a finding about the gene and the disease. The quoted sentences say what the papers report.
Sepsis (1 paper, 2025). Sepsis is defined as life-threatening organ dysfunction caused by a dysregulated host response to infection. "Ultimately, 8 key genes were identified: CD160, HELB, ING4, PIP5K1C, SRPRA (HR < 1); and CDCA7, FAM3A, PPP1R15A (HR > 1), and the hub genes showed apparent differences in expression between alive and dead sepsis patients." (PMID 40612938, 2025). "A lactylation-based prognostic model was developed, comprising eight key genes (CD160, HELB, ING4, PIP5K1C, SRPRA, CDCA7, FAM3A, PPP1R15A), and demonstrated strong predictive performance for sepsis outcomes (AUC = 0.78 in the training cohort; AUC = 0.73 in the validation cohort)." (PMID 40612938, 2025).
cancer (1 paper, 2025). A tumor composed of atypical neoplastic, often pleomorphic cells that invade other tissues. "Various studies have explored the role of SRP in cancer, but there has been minimal focus on its receptor SRPRA." (PMID 40408428, 2025).
SRPRA also shares sentences with these, for which no sentence is quoted: autism (1 paper); breast carcinoma (1).